BIRC3 (baculoviral IAP repeat containing 3)
Diseases named in the same sentence as BIRC3 in open-access papers (continued):
Sharing a sentence is not in itself a finding about the gene and the disease.
Chlamydia infection (1 paper, 2014). "Our results showed that the impact of Chlamydia infection on apoptosis (BIRC3, EMP1, CHAC1), immune response, host cell structure and cell cycle in EEC is similar to what has been observed in epithelial cells." (PMID 24959205, 2014).
cholesteatoma (1 paper, 2012). A pathologic process characterized by the proliferation of keratinizing squamous epithelium resulting in the accumulation of keratin and cells in the middle ear and/or mastoid. "Genes for anti-apoptotic proteins such as Bcl-xl (BCL2L1), A20 (TNFAIP3) and cIAP2 (BIRC3) show only a slightly higher expression in cholesteatoma (logFC 1.5–3)." (PMID 23285167, 2012). "Additionally, the message for anti-apoptotic proteins Bcl-xl (BCL2L1), A20 (TNFAIP3) and cIAP2 (BIRC3) show a slightly higher expression in cholesteatoma (logFC 1.5–3)." (PMID 23285167, 2012). "Real-time PCR of PI3, SPRR1B, LCN2 (lipocalin 2), MMP1, MMP9, MMP10, MMP12, SPP1, GJB2, Bcl-xl (BCL2L1), cIAP2 (BIRC3), S100A7A (koebnerisin), S100A9, SERPINB3, CEACAM6, KRT6B and SERPINB4 revealed that the expression levels of these proteins were higher in cholesteatoma than in external canal skin." (PMID 23285167, 2012).
cylindroma (1 paper, 2016). "Notably, siRNA knock‐down of MYB in cylindroma cells resulted in down‐regulation of both BCL2 and BIRC3 mRNA levels." (PMID 26969893, 2016).
disc degeneration (1 paper, 2022). "However, within these processes, only a few genes were commonly upregulated in human cluster D2 and N153S tissues, including BIRC3, CFD, RSAD2, and ALCAM – none of which are considered inflammatory hallmarks of disc degeneration." (PMID 35769461, 2022).
gastrointestinal stromal tumor (1 paper, 2022). "TNFR2 can also induce BIRC3/cIAP2 transcripts dependent on TRAF1 and decrease the transcription and expression of NKp46/NCR1, leading to tumor deterioration in mice and adverse outcomes in patients with gastrointestinal stromal tumors." (PMID 35494080, 2022).
gonococcal infection (1 paper, 2024). "This hypothesis is supported by studies from multiple groups showing that anti-apoptotic factors, including BCL2A1 (Bfl-1), BIRC3 (c-IAP-2), and PTGS2 (Cox-2), are upregulated upon gonococcal infection of epithelial monolayers lacking ciliated cells." (PMID 38704381, 2024).
HTLV infection (1 paper, 2012). "Genes highly expressed in both cell lines, like VCAM1 which is implicated in the formation of syncitia during HTLV infection, or the anti-apoptotic protein BIRC3/HIAP-1/CIAP-2 that prevents the death of naturally infected HTLV-1 CD8+ are easily visualized with this representation." (PMID 22911729, 2012).
liver fibrosis (1 paper, 2023). "Targeting cIAPs, including BIRC3, has been suggested as a potential therapeutic strategy for liver fibrosis by increasing MMP9 expression induced by CCL5 chemotactic neutrophils." (PMID 38274787, 2023). "BIRC3 may also play a role in liver fibrosis by regulating the inflammatory response." (PMID 38274787, 2023).
Lynch syndrome (1 paper, 2014). An autosomal dominant hereditary neoplastic syndrome characterized by the development of colorectal carcinoma and a high risk of developing endometrial carcinoma, gastric carcinoma, ovarian carcinoma, renal pelvis carcinoma, and small intestinal carcinoma. "Whole-genome DASL-based gene expression profiling based on 18.6 k genes identified 349 significantly deregulated genes with up-regulation of e.g. PTPRH, BIRC3, SHH and TNFRSF6B in Lynch syndrome tumors." (PMID 24848881, 2014).
microphthalmia (1 paper, 2024). Congenital or developmental anomaly in which the eyeballs are abnormally small. "Further upstream of the caspases in the apoptosis pathway, XAF1 (LFC +5.26, p < 0.0001), IRF1 (LFC +1.53, p < 0.000341), and STAT1 (LFC +1.850, p < 0.000000118) and pro-apoptotic genes BIRC3 (LFC +2.39, p < 0.00000695) and BIK (LFC +1.43, p < 0.00178) was upregulated in microphthalmia patients." (PMID 38821055, 2024).
peripheral nerve injury (1 paper, 2025). Injury to a peripheral nerve. "Furthermore, research on peripheral nerve injury revealed that TNFRSF1A, BIRC2, and BIRC3 in Schwann cells (SC) assume an anti-apoptotic function by modulating NFκB signaling pathway in response to inflammatory stimuli, thereby mitigating peripheral nerve damage." (PMID 40308566, 2025).
renal carcinoma (1 paper, 2016). A carcinoma arising from the epithelium of the renal parenchyma or the renal pelvis. "Similar effects were seen in a distinct renal cancer cell line, 786-0, however, in HK2 cells (normal kidney) SERPINE1 and IL-11 were downregulated along with EDN2, while BIRC3 was upregulated." (PMID 27384883, 2016).
small cell lung carcinoma (1 paper, 2023). Small cell lung cancer (SCLC) is a highly aggressive malignant neoplasm, accounting for 10-15% of lung cancer cases, characterized byrapid growth, and early metastasis. "BIRC3 and NOS2 were closely associated with small-cell lung cancer pathways." (PMID 37842046, 2023).
Stroke (1 paper, 2017). Sudden impairment of blood flow to a part of the brain due to occlusion or rupture of an artery to the brain. "We summarize here how NPD1 elicits neuroprotection by up-regulating c-REL, a nuclear factor (NF)-κB subtype that, in turn, enhances expression of BIRC3 (baculoviral inhibitor of apoptosis repeat-containing protein 3) in the retina and in experimental stroke, leading to neuroprotection." (PMID 28615451, 2017).
cancer (191 papers, 2005 to 2026). A tumor composed of atypical neoplastic, often pleomorphic cells that invade other tissues. "In cancer prognosis research, loss-of-function mutations or deletions in the BIRC3 gene are consistently associated with shorter survival and poor prognosis in cancer patients." (PMID 40243536, 2025). "More importantly, cancer patients with high expression of BIRC3 exhibited an increased risk of early recurrence following fluorouracil treatment." (PMID 38762737, 2024). "Two studies demonstrated that USP35 deficiency sensitized cancer cells to cisplatin (the first platinum anti-cancer drug) treatment via de-stabilizing anti-apoptotic factor BIRC3 or activating cGAS-STING-TBK1-mediated expression of type I interferons." (PMID 36864055, 2023). "Machine learning analysis pinpointed 14 feature genes, among seven were associated with cancer (NAT1, BIRC3, EZH2, MAD2L1, ATP2A3, HMGA1, and BST2)." (PMID 41255601, 2025). "Database searches indicated that NAT1, BIRC3, EZH2, MAD2L1, ATP2A3, HMGA1, and BST2 are cancer-associated genes." (PMID 41255601, 2025). "CIAP2, encoded by BIRC3, is one of the eight human inhibitors of apoptosis proteins (IAPs) that contribute to apoptosis escape of cancer cells." (PMID 38443362, 2024). "Previous studies have shown that BIRC3 (cIAP2) promotes survival and anti-apoptosis in cancer cells and is a therapeutic target of the drug family known as “Smac mimic”, although not all cases support this view." (PMID 39301019, 2024). "Existing evidence has demonstrated that BIRC3 plays a crucial role in promoting cancer cell survival and inhibiting apoptosis." (PMID 39301019, 2024). "The GSEA analysis results of BIRC3 observed that various cancer-promoting pathways were enriched in the high expression group including IL2 STAT5 signaling, IL6-JAK-STAT3 signaling, KRAS signaling, PI3K-AKT-MTOR signaling and TNFA signaling via NFKB." (PMID 38130918, 2023). "Although IAPs are collectively referred to as pro-oncogenic, the literature regarding BIRC3 (cIAP2) is conflicted; multiple clinical studies have demonstrated an unfavorable contribution of BIRC3 inactivation in cancer patients." (PMID 36803614, 2023). "We next injected the ZsGreen+ cells expressing shBIRC3 or shNC into nude mice through a tail vein to evaluate the effect of knocking down BIRC3 on cancer cell colonization in the lungs." (PMID 37391410, 2023). "We identified deletion of 18q21.2 and amplification of 11q22.2 as prevailing copy-number alterations in FA HNSCCs, the latter of which was associated with strong overexpression of the cancer-related genes YAP1, BIRC2, BIRC3 (at 11q22.1-2)." (PMID 34997070, 2022). "The present manuscript aims at collecting and describing the most recent evidences concerning the role of the two IAPs BIRC3 and BIRC5 focusing on cancer, in order to underline the common characteristics and to shed light on the main controversies." (PMID 33413657, 2021). "When comparing tumor samples with their adjacent normal tissue (total of 32 human cancers), BIRC3 results differentially expressed in a cancer-type specific manner." (PMID 33413657, 2021). "Genomics studies based on the Tumor Cancer Genome Atlas (TCGA) revealed how 7 IAPs members expression, including BIRC3, are distributed among 32 different types of cancers." (PMID 33413657, 2021). "Specifically, MUTYH and BIRC3 are both established as cancer drivers, and they both appear in clinical panels." (PMID 34290314, 2021). "Remarkably, cytokine signaling and interferon signaling regulated by BIRC3 were enriched in more than 80% of the cancers." (PMID 31964418, 2020). "BIRC3 and BIRC7 were the second most predictive genes each associated with tumor stage in five cancer types." (PMID 31964418, 2020). "Among the upregulated genes in the AMC-HN-8-BCL11A cells, some genes are classified as involving apoptosis, DNA damage, and DNA repair; BIRC3 promotes resistance of cancer cells to apoptosis." (PMID 32266150, 2020).
cancer (continued). "Most of the genes in the subnetworks were inflammatory cytokines and participated in TNF signaling pathways and pathways in cancer, such as Ccl2, Ccl20, Csf1, Cx3cl1, Cxcl1, Cxcl3, Il6, Birc3, Map3k8, Nos2, Nfkb2, Tnfrsf1b, and Vcam1." (PMID 33042984, 2020). "In this dataset, both probe sets for BIRC3 confirmed the finding in the TCGA (The Cancer Genome Atlas) dataset." (PMID 30718461, 2019). "Utilizing expression data from the cancer genome atlas (TCGA), we identified BIRC3 as a key facilitator of MT from LGG to HGG." (PMID 27074575, 2017). "In contrast to several other cancer cell lines, the BIRC3-positive TSCC cell line, 1889c showed spontaneous apoptosis after BIRC3 knock-down." (PMID 24427739, 2013). "1889c cells and HaCat keratinocytes were more sensitive toward BIRC3 knock-down than all other cancer cell lines tested, despite similar BIRC3 mRNA levels." (PMID 24427739, 2013). "The paradoxical upregulation of BIRC3 may reflect a compensatory mechanism by which cancer cells resist the apoptosis‐inducing effects of γT3 or δT3." (PMID 41036302, 2025). "Among these, NAT1, BIRC3, EZH2, MAD2L1, ATP2A3, HMGA1, and BST2 are known cancer-associated genes." (PMID 41255601, 2025). "Many evidences point to the pro-survival and antiapoptotic role of BIRC3 in cancer cells." (PMID 38280104, 2024). "Due to its numerous activities, the role of BIRC3 in cancer is highly context-dependent." (PMID 39598439, 2024). "The BIRC3/5 are upregulated in cancer tissues, leading to the promotion of cell proliferation." (PMID 38730465, 2024). "However, the role of BIRC3 in cancer is paradoxical, being reported as both a tumour suppressor and pro-oncogenic, even within the same cancer type." (PMID 36937454, 2023). "BIRC3 acts as a member of inhibitors of apoptosis proteins (IAPs) family and plays an important role in pro-survival and antiapoptotic on the cells, which has been characterized in multiple cancer types." (PMID 36389757, 2022). "Interestingly, BIRC3 can play a tumor-suppressing role or act as an oncogene in different types of cancer." (PMID 36685836, 2022). "Cancer cells of different histological origin rely on different pathways to survive and proliferate and BIRC3, in each type of cancer, may interact and contribute at different levels." (PMID 33413657, 2021). "Besides, CDKN2C and ID2 are downregulated while IL6, BIRC3, PLAT, PPARG, and CEBPB are upregulated in three candidate TCM associated with Transcriptional misregulation in the cancer pathway." (PMID 34490085, 2021). "Previous studies have revealed that accumulated BIRC3 contributes to tumor progression in several malignancies, and the expression levels of BIRC3 have been shown to be correlated with prognosis of patients with different cancers." (PMID 34692492, 2021). "However, several clinical studies published in recent years reported an unfavorable contribution of BIRC3 genetic inactivation or downregulation in cancer patients." (PMID 33413657, 2021). "BIRC3 is a novel prognostic indicator and a potential therapeutic target for cancer." (PMID 35069135, 2021). "Studies have demonstrated that BIRC3 promotes resistance of cancer cells towards apoptosis." (PMID 29983888, 2018). "Up regulation of several IAPs like NAIP (BIRC1), X-linked IAP (XIAP, BIRC4), Survivin (BIRC5), c-IAP1 (BIRC2), c-IAP2 (BIRC3), Apollon (BRUCE, BIRC6), Livin/MLIAP (BIRC7) and IAP-like protein 2 (BIRC8) have been reported in several cancer cells as well as in serum from cancer patients." (PMID 29464049, 2018). "However, approximately 80% studies focused on the roles of BIRC3 cancer." (PMID 35783533, 2022). "Therefore, the mechanism of BIRC3 in cancer needs further study." (PMID 34925455, 2021).
cancer (continued). "BIRC3, a member of the inhibitorof the apoptosis protein (IAP) family, is frequently overexpressedin cancer cells and contributes to apoptosis resistance." (PMID 41552544, 2026). "The top twenty differentially expressed genes in pathways in cancer (PC) include the well-known oncogene NRAS, the inhibitor of apoptosis BIRC3/cIAP2, and WNT7B, a component of the WNT/β-catenin pathway." (PMID 41467516, 2026). "The results showed that except for BIRC3 and UBE2N, other hub UBRs were dysregulated, and most of them were overexpressed in cancer patients." (PMID 40650277, 2025). "In contrast, BIRC3, another IAP family member known to resist apoptosis in cancer cells, displayed increased expression following treatment." (PMID 40143009, 2025). "Consistent with lucicebtide activity on C/EBPβ target genes in cancer cells, ID2, BIRC3, CyclinA2 and CDK1 were significantly downregulated in lucicebtide-treated M2-cells." (PMID 40103809, 2025). "These marker genes play diverse roles in cancer, such as promoting growth and proliferation (MYC, HIF1A, ATM), inhibiting apoptosis (MCL1, BIRC3, BCL2) and facilitating invasion (CXCR4, CD55)." (PMID 38982317, 2024). "The analysis revealed that several members of the IAP family, including NAIP, BIRC2, BIRC3, XIAP, BIRC5, BIRC6, and BIRC7, exhibited higher expression levels in multiple cancers, including HCC." (PMID 37781078, 2023). "Further work is needed to understand the expression patterns of RASSF6 and PTPRG, which are generally considered to be tumor suppressors and genes like BIRC3 and CDKN1A that are known to be involved in a number of different cancers." (PMID 37910143, 2023). "BIRC3 is a member of the apoptosis inhibitor (IAP) family, with pro-survival and antiapoptotic effects in cancer cells." (PMID 37860187, 2023). "BIRC3 and BIRC6 are the ones involved in the regulation of at least one of these pathways in 78% and 69% of the types of cancers, respectively." (PMID 33413657, 2021). "The present manuscript collects and reviews the most recent literature concerning the role played by BIRC3 and BIRC5 in cancer cells, providing useful information for the choice of the best therapeutic targets." (PMID 33413657, 2021). "XIAP and BIRC2 were found to express highly among different cancers while NAIP and BIRC3 were only selectively expressed in a few cell lines." (PMID 31964418, 2020). "The frequency of apoptosis pathway regulations varied among different IAPs, with BIRC3 and BIRC6 both regulating 36.4% of cancers while BIRC7 only regulating 12.5% of cancers in at least one of the apoptosis pathways (overall proportion test P = 0.0022)." (PMID 31964418, 2020). "BIRC3 is a member of the inhibitors of apoptosis proteins (IAP) family and relates to many cancers in cases of aberrant overexpression because it can prevent apoptotic signals." (PMID 33333978, 2020). "The capacity of apoptosis regulations among IAPs also differed with BIRC3 and BIRC6 both regulating 36.4% of cancers while BIRC7 only regulating 12.5% of cancers in at least one of the apoptosis pathways." (PMID 31964418, 2020). "BIRC3, baculoviral IAP repeat‐containing protein 3, as an apoptosis inhibitor, was overexpressed in multiple cancers and led to development of malignant tumors." (PMID 33098370, 2020). "This work described the involvement of the TLR4/NF-κB pathway activation which led to the overexpression of BIRC3 (Baculoviral IAP Repeat Containing 3), a member of apoptosis’ inhibitor proteins known to be involved in the chemoresistance of several cancers." (PMID 31533218, 2019). "Notable alterations in human cancer gene orthologs impacted by SVs in single cases include an ARHGEF12 inversion, a BIRC3 inversion, a CLPTM1L-TERT translocation, a DDIT3 inversion, a MYO5A translocation, and a TCF12 inversion." (PMID 30188888, 2018).